IL4 (interleukin 4)
Diseases named in the same sentence as IL4 in open-access papers (continued):
Sharing a sentence is not in itself a finding about the gene and the disease.
atopic dermatitis (continued). "In atopy patch testing (APT) of cats with spontaneously occurring atopic dermatitis, an increase of IL-4+ T-cells infiltrating into the APT biopsy site was also observed." (PMID 39911485, 2024). "In atopic dermatitis pathogenesis, inflammatory cytokines of the Th2, Th17, Th1, and Th22 subclasses, such as IL-4, IL-13, IL-17A, INF-γ, IL-12A, and IL-22, play important roles." (PMID 38672764, 2024). "IL-4 and IL-13 are closely related to atopic dermatitis, and they activate the intracellular JAK1/STAT6 pathway." (PMID 39599592, 2024). "Dupilumab, an antibody blocking IL-4 and IL-13, is approved for treating moderate to severe atopic dermatitis (AD) where itching is a significant symptom." (PMID 38846700, 2024). "In the present study, a statistically significant increase in serum IL‐4 (p < 0.001) and IL‐13 (p < 0.001) concentrations was determined in dogs with atopic dermatitis, compared to the healthy ones." (PMID 38648253, 2024). "The serum levels of TNF-α and IL-4 were measured in atopic dermatitis mice using ELISA kits, which were observed to be significantly decreased after topical application of FCS." (PMID 38255849, 2024). "The results showed that CSSH reduced pro-inflammatory cytokines (IL-1β, IL-6, IL-8, MCP-1 and CXCL10) and atopic dermatitis-related cytokines (IL-4, CCL17, MDC and RANTES) in TNF-α/IFN-γ-induced HaCaT cells." (PMID 38931136, 2024). "Nevertheless, it serves as an initial exploration for future studies, being among the first, to our knowledge, to assess IL-4 and IL-13 as biomarkers for atopic dermatitis." (PMID 38541676, 2024). "The immunology of chronic prurigo shows similarities with atopic dermatitis due to the involvement of IL-4 and IL-13, IL-22, and IL-31." (PMID 38493053, 2024). "We established an in vitro model of atopic dermatitis-like barrier disruption by treating human keratinocytes with IL-4 and IL-13, two key cytokines involved in Th2 inflammation." (PMID 39329899, 2024). "In support, a mouse model found that diet-induced obesity increased the severity of atopic dermatitis in an IL-17 dependent manner, and that rosiglitazone suppressed IL-17 and restored the effectiveness of anti-IL-4 and anti-IL-13 therapy." (PMID 39763655, 2024). "Th2 diseases associated with the activation of Type 2 immunity and mediated by IL-4/IL1-13, such as allergic asthma and atopic dermatitis, have been treated with biologic drugs blocking IL-4; these agents target and switch off Th2-induced inflammation." (PMID 38727279, 2024). "Upon the IL-4/IL-13 treatment, the epidermis exhibited a thinned and unpacked morphology resembling the skin barrier disruption observed in atopic dermatitis." (PMID 39329899, 2024). "An increase in Th2 cytokines, including IL-4 and IL-13, is an important feature in atopic dermatitis lesions." (PMID 39599592, 2024). "In our investigation, we assessed the potential of IL-4 and IL-13 as biomarkers for gauging the treatment response in patients with atopic dermatitis (AD) undergoing Dupilumab administration." (PMID 38541676, 2024). "Abrocitinib, an oral JAK1 inhibitor, that curtails the signaling of IL-4 and IL-13, has been reported to provide early itch symptom relief in the atopic dermatitis." (PMID 38541674, 2024). "In our investigation, we conducted a clinical assessment of IL-4 and IL-13 as potential biomarkers for disease severity and the treatment response in atopic dermatitis (AD)." (PMID 38541676, 2024). "Atopic Dermatitis is largely a Th2-driven disease that is characterized by elevated levels of interleukin (IL)-4, IL-5, IL-13, and IL-31." (PMID 39119011, 2024). "The associations between the clinical and laboratory values of the IL-4 levels in the atopic dermatitis (AD) patients were examined using Pearson’s correlation coefficient." (PMID 38541676, 2024).
atopic dermatitis (continued). "Considering the similarities between the role of IL-4 in the pathophysiology of atopic dermatitis and allergic conjunctivitis, the utility of Dupilumab in the management of the latter disease is worth exploring." (PMID 38541674, 2024). "For example, in atopic dermatitis and bronchial asthma patients, increased SCCA is caused by IL-4 and IL-13, which are secreted by Th2 cells." (PMID 38347831, 2024). "Based on current evidence, it appears that the use of anti-TNF-α for psoriasis and anti-IL-4/13 for atopic dermatitis are inversely related." (PMID 38521706, 2024). "Intrinsic atopic dermatitis is characterized by a normal skin barrier, lower expression of IL-4, IL-5, and IL-13, and higher expression of IFN-gamma." (PMID 38672221, 2024). "Atopic dermatitis is defined as an immune disorder driven by Th2 cells and characterized by elevated levels of interleukin (IL)-4, IL-13, and IL-5." (PMID 38541664, 2024). "In a study on atopical dermatitis, IL-4, produced by T helper 2 (Th2) lymphocytes, decreases ceramide, which is a key lipid component in the skin’s water-holding properties." (PMID 39272951, 2024). "Increased concentrations of IL‐4, IL‐12, IL‐13 and IL‐18 have been found in humans with atopic dermatitis." (PMID 38648253, 2024). "We also demonstrated that induced Th2 immune responses, which mimic an atopic dermatitis-like phenotype, can lead to successful viral penetration as shown by infected cells in interleukin-4 (IL-4)/IL-13-treated human skin." (PMID 37289055, 2023). "We observed an increased mRNA expression of type 2 inflammatory mediators, including interleukin-4 (Il4), Il13, and Il33, in the skin of NC/Nga mice with atopic dermatitis compared with control mice." (PMID 37298299, 2023). "For example, elevated levels of IL4 are commonly found in patients with atopic dermatitis and allergic rhinitis." (PMID 37762523, 2023). "The enrichment of the immune pathways was also high in atopic dermatitis or psoriasis, but the IL-3/IL-5/GM-CSF and IL-4/IL-13 signaling was highest in HS lesional skin." (PMID 38069342, 2023). "Periostin has been shown to play a role in Th2 pathway-mediated inflammatory diseases, such as atopic dermatitis, where interleukin-4 and interleukin-13 cytokines have been reported to activate periostin production in fibroblasts." (PMID 37773198, 2023). "Atopic dermatitis generally occurs due to an abnormal increase in the levels of Th2 cytokines such as IL-4, IL-5, and IL-13." (PMID 37432237, 2023). "Dupilumab was first approved for the treatment of atopic dermatitis (AD) and blocks the signaling of interleukin (IL)-4 and -13." (PMID 37189381, 2023). "Dupilumab is a fully human antibody directed against the common alpha chain of IL-4 and 13 receptors, two key players in atopic dermatitis with their role in modulating skin barrier integrity." (PMID 38203533, 2023). "Studies on atopic dermatitis found that the presence of Th2 cytokines (IL-4 and IL-6) at a concentration of 10 nM has been shown to reduce ceramides in the skin, a key component of a functional skin barrier." (PMID 38067173, 2023). "This is in line with the finding that the H1R mRNA level can be upregulated by histamine or IL-4 and findings of the higher expression of H1R mRNA in keratinocytes from patients with atopic dermatitis." (PMID 36615633, 2023). "Cells under atopic dermatitis conditions (IL-4 and IL-13) showed decreased decline in scratch width in HaCaTs (65.2 ± 2.9%) and primary keratinocytes (54.0 ± 1.8%) compared to controls after 48 h." (PMID 36615633, 2023). "Here, we investigated the effect of histamine in an atopic dermatitis skin milieu sustained by TH2 cytokines (IL-4, IL-13 and IL-31), using human keratinocytes and full-thickness skin models with a developed epidermal layer." (PMID 36615633, 2023).
atopic dermatitis (continued). "Atopic dermatitis, a significant risk factor for CHE, has a complex pathophysiology with the predominant involvement of Th2 cells and certain cytokines, such as IL-4 and IL-13, associated with skin barrier defects." (PMID 38203533, 2023). "First reports from studies on Dupilumab, an IL4/13 antibody, which has been used for many years in the treatment of atopic eczema, show promising efficacy and safety data." (PMID 37881435, 2023). "Cutaneous afferent neurons express receptors interleukins (IL)-4, IL-13, and IL-33, which are type 2 cytokines that are elevated in atopic dermatitis." (PMID 37868811, 2023). "Dupilumab, a prominent therapy targeting IL-4 and IL-13, has demonstrated well-documented efficacy, tolerance, and safety in atopic dermatitis." (PMID 38203533, 2023). "Dupilumab is a monoclonal antibody that targets the IL-4α receptor and improves the symptoms of atopic dermatitis by inhibiting IL-4 and IL-13." (PMID 38482457, 2023). "Increased IgE production and IL-4 gene expression in atopic dermatitis were significantly reduced after topical Ca-EE application." (PMID 36840208, 2023). "The expression of Il4, Il13, and Il33 was increased in the skin of NC/Nga mice with atopic dermatitis, while calcitriol application decreased Il13 and Il33 mRNA expression." (PMID 37298299, 2023). "Different JAKs are involved in the signal transduction of numerous cytokines and growth factors, including IL-4 and IL-13, the main mediators of atopic dermatitis." (PMID 37834935, 2023). "We also observed viral invasion via the skin surface after IL-4/IL-13 stimulation of human skin from healthy individuals, which was less efficient than in atopic dermatitis skin." (PMID 37289055, 2023). "We also found nectin-1 ubiquitously localized in the epidermis of atopic dermatitis and IL-4/IL-13-treated human skin implying that impaired tight-junctions in combination with a defective cornified layer allow the accessibility of nectin-1 to HSV-1." (PMID 37289055, 2023). "In atopic dermatitis, or eczema, the main role is played by T-helper 2 cells and an upregulation of IL-4 and IL-13 is found, in addition to interferon (IFN)-γ, IL-17, and IL-22 in chronic eczema." (PMID 36770889, 2023). "IgG autoantibodies against IgE from atopic dermatitis can induce the release of IL-4/IL-13 and LTC4 from human basophils, indicating that these cells contribute to this allergic disorder." (PMID 36578500, 2022). "The eosinophilia and atopic dermatitis in our patients are suggestive of increased Th2 function via elevated production of IL-5 and IL-4, respectively." (PMID 36605204, 2022). "Since 2018, trials in China started to investigate IL-12/23 (all four trials for psoriasis) and IL-4/13 (5/7 for atopic dermatitis, one for prurigo nodularis and one for CSU)." (PMID 35529441, 2022). "An important biologic for the treatment of atopic dermatitis is dupilumab, an IL-4 receptor-α inhibitor that blocks both IL-4 and IL-13 activity and is approved for the treatment of moderate-to-severe atopic dermatitis in patients 6 years of age and older." (PMID 36552866, 2022). "Th2 cells mediate inflammation in atopic dermatitis with the release of IL-4 and IL-13, which contribute to clinical manifestations." (PMID 36578500, 2022). "Dupilumab is a monoclonal antibody with the ability to bind and block the IL-4/IL-13 receptor, already approved for the treatment of atopic dermatitis." (PMID 36553635, 2022). "Interleukin 4 (IL-4) is a proinflammatory cytokine derived from T-helper type 2 cells; it plays a critical role in the pathogenesis of atopic dermatitis." (PMID 35807451, 2022). "Atopic dermatitis (AD), driven by interleukins (IL‐4/IL‐13), is a chronic inflammatory skin disease characterized by intensive pruritus." (PMID 35111948, 2022). "Targeting IL-4 in Th2 cell-mediated immune response has led to the clinical application of IL-4 antagonist, dupilumab, in treatment of atopic dermatitis." (PMID 36539414, 2022).
atopic dermatitis (continued). "The Th2 polarization is characterized by IL-4/IL-13 dependent pathway activation in atopic eczema, allergic asthma, and food allergies and consistently we observed similar and significantly higher values of these cytokines." (PMID 35458127, 2022). "TQ was recently discovered to attenuate atopic dermatitis by reducing the levels of inflammatory cytokines, such as IL-4, IL-5, and IFN-gamma, and immunomodulatory cells in the blood." (PMID 36518853, 2022). "The only available biologic for atopic dermatitis in China is dupilumab targeting at IL-4 and 13, which was approved by the CDE in 2020." (PMID 35529441, 2022). "However, IL-4 levels could be associated with some medical setting, such as scleroderma, multiple sclerosis, chronic sinusitis, inflammatory bowel diseases, bronchial asthma, atopic dermatitis." (PMID 36211709, 2022). "Other targets in phase III trials included IL-4/13 (n = 1 for atopic dermatitis, prurigo nodularis, and CSU, respectively), IL-5 (n = 1 for bullous pemphigoid), and IgE (n = 1 for CSU)." (PMID 35529441, 2022). "In a mouse model of atopic dermatitis, IL-4 responses were required for IL-36R signaling to elevate IgE levels." (PMID 35222417, 2022). "Recent data in atopic dermatitis patients undergoing dupilumab treatment (IL-4 and IL-13 blocker) reported the development of peripheral enthesitis." (PMID 33544244, 2021). "Taken together, it is plausible that infiltrated basophil represent a source of IL-4 that aids in eosinophil recruitment in atopic dermatitis." (PMID 33919759, 2021). "Monoclonal antibodies (mAbs) targeting IL-4Ra, such as dupilumab, ameliorate atopic dermatitis by blocking both IL-4 and IL-13 signaling." (PMID 34305927, 2021). "While the Th2 cytokine IL-4 is important for acute atopic eczema development, the Th1 and Th17 cytokines IFN-γ, IL-17, and IL-22 predominate in chronic eczema states." (PMID 33520088, 2021). "First, to validate that introduction of Th2 related cytokines (IL-4, IL-13, and IL-25) can stimulate atopic dermatitis environment, we looked at differentially expressed genes with p-value < 0.005." (PMID 33806193, 2021). "In patients with psoriasis, similarly to atopic dermatitis, the levels of IL-4 and IL-31 were significantly elevated in comparison to healthy controls." (PMID 33467067, 2021). "For example, a human anti‐IL‐4Rα monoclonal antibody which interrupts signaling of both IL‐4 and IL‐13 has demonstrated convincing efficacy in controlling moderate‐to‐severe atopic dermatitis, allergic asthma, and nasal polyps." (PMID 34429871, 2021). "Surprisingly, we observed higher TOX expression but significantly lower IL-4 expression in Atopic Dermatitis (AD) as a control of a Th2 BID." (PMID 34220814, 2021). "In a murine model for atopic dermatitis, oral administration of Se suppressed the development of atopic dermatitis-like skin lesions, lowered total IgE levels, reduced skin expression of IL-4 and led to a lower number of mast cells in the skin." (PMID 34444651, 2021). "Consistently, the accumulation of basophils that express IL-4 in skin lesions of atopic dermatitis patients was observed." (PMID 33919759, 2021). "The JAK1 inhibitor abrocitinib, which reduces IL-4 and IL-13 signaling, is being investigated for the treatment of atopic dermatitis." (PMID 34680614, 2021). "Dupilumab is a dual inhibitor of interleukin-4 and interleukin-13 and is mainly used to treat moderate-to-severe atopic dermatitis." (PMID 34253801, 2021). "High levels of IL-4 were reported in alveolar lavage fluid of bronchial asthma, and IL-4 induced high [3H]-tritium uptake when incubated with peripheral blood mononuclear cells from atopic dermatitis patients." (PMID 34064515, 2021). "The clinical impact of key Th2 cytokines interleukin (IL)-4 and IL-13 on atopic dermatitis has been recently shown in clinical studies with dupilumab, a monoclonal antibody that blocks the IL-4/IL-13 receptor." (PMID 34745434, 2021).
atopic dermatitis (continued). "In three different-IgE-dependent models of atopic dermatitis, basophil-derived IL-4 was shown to induce VCAM-1 expression on endothelial cells of the skin, which resulted in infiltration of eosinophils." (PMID 33919759, 2021). "Recently, several studies have indicated that IL-31 is importantly related to atopic dermatitis, and that production of IL-31 is increased by IL-4." (PMID 34959939, 2021). "In humans, recent research results suggested that electroacupuncture reduced the level of IL-4 and IL-2 in the blood of patients with atopic dermatitis and increased the level of interferon γ (IFN-γ)." (PMID 35431769, 2021). "PARP1 positively regulates the production of Th1/Th2 cytokines such as IL-4/IL-5/GM-CSF and allergen-specific IgE in a mouse model of atopic dermatitis." (PMID 32900001, 2020). "Atopic dermatitis (AD) is an eczematous, pruritic skin disorder with extensive barrier dysfunction and elevated interleukin (IL)-4 and IL-13 signatures." (PMID 32751111, 2020). "For instance, as described in atopic dermatitis, T helper type 2-produced cytokines (especially IL-4 and IL-13) affect keratin, desmoglein, loricrin and involucrin levels." (PMID 32119674, 2020). "It was reported that 60% ethanol/water extraction of P. densiflora bark regulated wound healing-involved cytokines such as interleukin (IL)-4, IL-5, and tumor necrosis factor alpha, resulting in attenuated atopic dermatitis." (PMID 32325920, 2020). "In atopic dermatitis, cytokines IL-4 and IL-13 play a key role in the modulation of the epidermal barrier and the stimulation of dermal inflammation and remodeling." (PMID 32382467, 2020). "In a study of atopic dermatitis, AD-MSCs exosomes significantly reduced mRNA expression of various inflammatory cytokines such as interleukin (IL)-4, IL-23, IL-31, and tumor necrosis factor-α (TNF-α) in atopic dermatitis skin lesions of the mouse model." (PMID 32483483, 2020). "In atopic dermatitis (AD), Th2 cytokines such as IL-4 and IL-13 are regarded to be the main player of the disease; however, Th17 cytokines are also expressed in AD skin lesions." (PMID 32075269, 2020). "In atopic dermatitis, Th2 cytokines such as IL-4 and IL-5 are known to have an important function in amplifying allergic inflammation in skin lesions." (PMID 32514255, 2020). "In a mouse model of allergic dermatitis, the expression of Interleukin-4 (IL-4) was increased in inflamed skin, demonstrating an altered immune response." (PMID 33198395, 2020). "Mast cell-mediated inflammatory cytokines (e.g., TNF, IL-1, IL-4, and IL-6) occur as part of the tissue remodeling related to atopic dermatitis and allergic asthma, and in many other scenarios characterized by chronic allergic inflammation." (PMID 32932637, 2020). "The activation of T2 cells leads to IL-4, IL-5, and IL-13 secretion, provoking skin barrier alteration, immune cell infiltration into skin, and itch as observed in atopic dermatitis." (PMID 31028434, 2019). "IL-4 also promotes production of IgE, which shows elevated serum levels in the majority of patients with atopic dermatitis." (PMID 31028434, 2019). "Dupilumab, a monoclonal antibody directed against IL-4 and IL-13, developed for atopic dermatitis interferes with key cytokines in the Th2 pathway and offers new possibilities for off-label use." (PMID 31440261, 2019). "To date, the most successful treatment for atopic dermatitis is dupilumab, an antibody that regulates two signaling pathways (the IL-4 and IL-13 pathways) by binding to a receptor called IL-4Ra." (PMID 31782733, 2019). "Especially in the atopic dermatitis, it has been shown that IL-4 production by Th2 cells is predominant at the initiation phase, but IFN-γ production by Th1 cells is predominant at the late and chronic phases." (PMID 31426284, 2019). "Paramylon has been shown to improve the symptoms of atopic dermatitis and decrease the secretion of IL-4, IFN-γ, IL-18, and IL-12 in NC/Nga mice." (PMID 29389956, 2018).